HAS2 (hyaluronan synthase 2)
Diseases named in the same sentence as HAS2 in open-access papers (continued):
Sharing a sentence is not in itself a finding about the gene and the disease.
breast cancer (continued). "Moreover, elevated HAS2 expression is also found in breast cancer cell lines compared to normal breast tissue, and its knockdown leads to decreased proliferation and increased apoptosis." (PMID 35767191, 2022). "In breast cancer cells, osteopontin has been shown to upregulate HAS-2, another enzyme involved in the synthesis of hyaluronan, a major component of the extracellular matrix, with a role in several cellular functions, including cell proliferation and migration." (PMID 34066306, 2021). "In addition, one study indicated that PFKFB4 promotes breast cancer metastasis in a p38-dependent manner that initiates HAS2 transcription and expression." (PMID 33803236, 2021). "Experimental evidence shows that HA synthesis contributes to tumor supporting microenvironment, blocking HA production by knockdown of HAS2 and the use of inhibitors such as 4–Methylumbelliferone inhibits tumorigenesis and metastasis of breast cancer cell lines." (PMID 34827550, 2021). "Moreover, in breast cancer, upregulation of hyaluronan synthase 2 (HAS2) induces the production of the hyaluronic component of the ECM, which is can promote TAMs-released platelet-derived growth factor-BB (PDGF-BB)." (PMID 33613850, 2021). "Moreover, antisense inhibition of HAS2 in aggressive breast cancer has been reported to inhibit the in vivo formation of tumors." (PMID 33917849, 2021). "In summary, we found that a still uncharacterized protein mainly expressed by breast cancer cell lines can induce HAS2 expression and HA secretion by surrounding fibroblasts and that modification of the stromal ECM can contribute to modulate cancer progression." (PMID 33807583, 2021). "Overexpression of HAS2 is correlated with malignant function of breast cancer cells." (PMID 33892667, 2021). "Finally, we found a correlation between increased HAS2 gene expression and a pro-tumorigenic inflammatory gene signature in primary human breast cancer samples." (PMID 32455980, 2020). "Here we have extended these findings to assess whether regulation of Has2 mRNA by 1,25D3 alters HA production and/or phenotype of breast cancer cells." (PMID 32774770, 2020). "Since HA content is increased during breast cancer progression and elevations in HAS2 and HA correlate with poor prognosis, further studies to evaluate the association of vitamin D signaling and the HA pathway in aggressive human breast cancers are of significant interest." (PMID 32774770, 2020). "In murine mammary tumor cells, we observed rapid and sustained down-regulation of Has2 by 1,25D3." (PMID 32774770, 2020). "Importantly, our in vitro and in vivo results in a murine model were supported by data from human breast cancer cases, where increased HAS2 expression is significantly correlated with an inflammatory gene signature." (PMID 32455980, 2020). "Consistently with the clinical data, comparative analyses of distinct breast cancer mouse models demonstrated enhancement of the HBP gene expression in primary carcinoma cells, with elevation of Has2 expression and hyaluronan production in aggressive breast cancer cells." (PMID 31645543, 2019). "Considering that the basal-like and claudin-low subtypes belong to the group of triple-negative breast cancer having a high incidence of recurrence and metastasis, the co-expression of GFAT and HAS2 may confer aggressiveness in human breast cancer." (PMID 31645543, 2019). "That the HAS2 inhibitor 4-MU suppressed TGFβ-induced invasiveness of 3D-breast cancer cell-derived organoids suggested that TGFβ may regulate the production of HA in the MDA-MB-231 cells." (PMID 31361756, 2019). "Furthermore, one of the key enzymes in hyaluronan synthesis, hyaluronan synthase-2 (HAS2) facilitates metastasis in mouse breast cancer models." (PMID 27486983, 2016). "HAS2 promotes breast cancer cell invasion and tumour progression in bowel cancer." (PMID 26512722, 2015). "Elevated HAS2 expression was also witnessed in highly invasive breast carcinoma cells." (PMID 26322272, 2015).
breast cancer (continued). "Suppression of HAS2 in MDA-MB-231 breast cancer cell line displayed decreased cellular proliferation with a transient arrest in a cell cycle, ablation of migratory phenotype, alteration in hyaluronan catabolism, and inhibition of primary and secondary tumour formation." (PMID 25126569, 2014). "In breast cancer cells, HAS2 expression is often strongly correlated with malignant behavior." (PMID 23426189, 2013). "These analyses reveal that in contrast to TGFβ, rhPRG4 leads to reduction in the protein abundance of CD44 and HAS2 in the absence or presence of exogenous TGFβ, which could provide a mechanism by which rhPRG4 suppresses TGFβ-induced invasiveness of breast cancer cells." (PMID 31361756, 2019). "We observed that silencing of USP4 in breast cancer cells led to a small but significant increase in the amount of hyaluronan secreted into the culture media, which is consistent with an importance of Lys190 and possibly monoubiquitination for the regulation of hyaluronan synthesis by HAS2." (PMID 28604766, 2017). "Furthermore, HAS2 promotes breast cancer cell invasion in vitro." (PMID 26106384, 2015). "For example, studies in breast cancer have shown that increased flux through the HBP, along with higher levels of GFAT and HAS2, enhances Akt/GSK3β/β-catenin signaling and increases O-GlcNAcylation, promoting cancer stem–like properties." (PMID 41461315, 2025). "In contrast, suppression of HAS2 by using antisense-transcript HAS2-AS1 has been shown to attenuate the proliferation and malignant phenotype of glioma, osteosarcoma and breast cancer." (PMID 36698043, 2023). "The breast cancer cell lines Hs578T and MDA-MB-231 (parental line and a bone-seeking clone) expressed high levels of HAS2 and lower mRNA levels of HAS1 and HAS3." (PMID 36497283, 2022). "Breast cancer cell lines with an aggressive phenotype (MDA-MB-231 and HS578T) show a high level of HAS2 mRNA." (PMID 36613567, 2022). "Breast cancer cell lines with an aggressive phenotype (MDA-MB-231, HS-578 T) showed higher HAS2 gene expression and higher hyaluronan levels than cell lines with a less aggressive phenotype." (PMID 35264144, 2022). "Additionally, HAS2 may be involved in the aggressive phenotypes of primary breast cancer." (PMID 33619234, 2021). "For instance, HAS2 synthesized hyaluronic acid, enhanced ZEB1 expression and accelerated EMT in breast cancer." (PMID 32862195, 2021). "Collectively, our studies indicate that HAS2 and GFPT2 represent attractive drug targets in human breast cancer." (PMID 32774770, 2020). "Genomic profiling of murine mammary tumor cells with differential VDR expression identified 35 transcripts that were altered by the 1,25D3-VDR complex including Hyaluronan Synthase-2 (Has2)." (PMID 32774770, 2020). "It has been shown that TGFβ promotes the expression of HAS enzymes, particularly HAS2, which results in the accumulation of high levels of HA in the ECM of breast cancer cells." (PMID 31361756, 2019). "In breast cancer, TAMs can promote BCSCs through a paracrine EGFR/Stat3/Sox-2 signaling pathway, while upregulation of HAS2 (hyaluronan synthase 2) in CD44+/CD24−/ESA+ BCSCs can enhance the interaction between BCSCs and TAMs, resulting in the BCSC growth." (PMID 31555586, 2019). "Next, we analyzed the correlation of compression-upregulated metabolic genes with compressive stress markers (COL1A1, COL3A1, HAS2, and HAS3 genes) and tumor size in breast cancer subtypes: luminal A (LumA), luminal B (LumB), Her2, and triple-negative (TN)." (PMID 31428701, 2019). "Further, our identification of increased IL8, IL6, HAS2, and ICAM1, as well as decreased ERBB2 in MpBC samples matches findings from a microarray comparison of gene expression between metaplastic breast cancers and ductal carcinomas of the breast." (PMID 31488082, 2019).
breast cancer (continued). "Gene set analysis revealed that in human breast cancer cell lines the expression of these seven genes (MUC1, PLAU, FABP7, SPARC, HAS2, HAS3, SOX4) are higher in basal-B subtype compared to other subtypes." (PMID 29435170, 2018). "In breast cancer tissue sections we found robust co-expression of ZEB1 and HAS2 in tumor cell areas, whereas tumor cells missing ZEB1 were also negative for HAS2." (PMID 28086235, 2017). "Overexpression of HAS2 in mammary epithelial cells of MMTV-Neu transgenic mice increases tumor HA production and enhances growth of mammary tumors." (PMID 26106384, 2015). "4-MU also inhibits HA synthesis via repression of HAS2 and/or HAS3 mRNA in breast cancer, melanoma and ovarian cancer cells." (PMID 23426189, 2013). "In the CACO-2 cell line, HAS2 expression was not influenced by 4-MU treatment in the same way as was the case in breast cancer cell lines." (PMID 41373491, 2025). "In addition, Excessive production of HA by HAS2 induces over-expression of TGF-β which activates transcriptional factors Snail and Twist to initiate the EMT process in breast cancer cells." (PMID 36698043, 2023). "HAS2 was found to promote ZEB1-mediated EMT and metastasis in breast cancer." (PMID 32862195, 2021). "Among the compression-upregulated metabolic genes, the expression of ENO2 gene was significantly and positively correlated with COL3A1 and HAS1 genes, whereas PFKFB3 genes were significantly and positively correlated with that of COL1A1, HAS2, and HAS3 genes in breast cancer patient tissues." (PMID 31428701, 2019). "However, in CACO-2 cells, HAS2 expression was not influenced by 4-MU treatment in the same way as was the case in breast cancer cell lines, suggesting a cell type-dependent response." (PMID 41373491, 2025). "In addition, HAS2 could activate the PI3K/Akt pathway and increase the invasion capacity of breast cancer cells by inhibiting timp-1 and promoting FAK phosphorylation." (PMID 32862195, 2021). "CD44s additionally promoted the expression of hyaluronan synthase 2 (HAS2) by activating the PI3K/AKT signalling pathway, which further enhanced CD44s-mediated PI3K/AKT signalling, thus creating a positive feedback loop to drive tumour cell survival in breast cancer cells." (PMID 34944493, 2021). "Non-aggressive breast cancer cells express high levels of HAS3 and lower levels of HAS2 compared with aggressive breast cancer cells." (PMID 33986244, 2021). "Our results show a positive correlation between BRCA1 and CD44, HAS2, HAS3 and HYAL1 in colorectal but not breast cancer." (PMID 32610620, 2020). "In contrast, the epithelial breast cancer and fibrotic cell lines MCF7 and MCF10A showed high E-cad levels and low levels of ZEB1, CD44s and HAS2, reflecting a weak or absent EMT signature." (PMID 28086235, 2017). "Expression of tumor cell HAS1, but not HAS2 or HAS3, was found to correlate with reduced overall survival when breast cancer patients were not sorted into subtypes." (PMID 26106384, 2015). "The reliability of the primer of Has2 and HAS1 was confirmed by the positive control cells: Has2 for Lewis lung cell carcinoma cell line, and HAS1 for MDA-MB-231 breast cancer cell line (data not shown)." (PMID 22045192, 2011). "Therefore, both ETP and HAS2 are essential for the induction and maintenance of EMT in breast cancer and TGFβ alone is not enough for the EMT process." (PMID 25126569, 2014). "However, c10orf118 silencing modified the expression of HAS2 and its epigenetic regulator HAS2-AS1, as well as the levels of the HA receptor CD44, suggesting a specific effect on HA metabolizing genes rather than the behaviour of breast cancer cells." (PMID 33807583, 2021).
lung fibrosis (15 papers, 2015 to 2025). "In a bleomycin-induced pulmonary fibrosis model, Has2 induces and regulates cellular senescence in fibroblasts via the p27-CDK2-SKP2 pathway." (PMID 41181120, 2025). "In a bleomycin-induced pulmonary fibrosis model, fibroblasts with Hyaluronan synthase 2 overexpression showed a higher capacity to invade matrix and promote the development of lung fibrosis." (PMID 35980387, 2022). "The importance of HAS2 in the development of lung fibrosis was confirmed on the murine in vivo model of bleomycin-induced injury by using conditional HAS2-KO mice which did not suffer from fibrosis after bleomycin treatment." (PMID 35053193, 2021). "The invasive phenotype of fibroblasts isolated from patients with idiopathic pulmonary fibrosis was HAS2 and CD44 related." (PMID 35053193, 2021). "In our experimental model of BLM-induced lung fibrosis and PH, we report increased levels of Has2, Il-6 and Tgm2 following BLM exposure compared to PBS exposure in TaglnCre mice." (PMID 29910735, 2018). "In contrast to the previously reported beneficial effects of HMW-HA, these findings suggest that increasing the amount of HMW-HA synthesized by HAS2 acts as an important signal to induce pulmonary fibrosis." (PMID 29062810, 2017). "Overexpression of HA synthase 2 (HAS2) by lung fibroblasts produced an aggressive invasive phenotype leading to severe lung fibrosis and death after bleomycin-induced injury." (PMID 26887531, 2016). "Conditional deletion of HAS2 in mesenchymal cells in α-smooth muscle actin (α-SMA)-HAS2 transgenic mice abrogated the invasive fibroblast phenotype, impeded myofibroblast accumulation, and inhibited the development of lung fibrosis." (PMID 26448760, 2015). "More recently, Has2 has been described as promoting the invasive phenotype of fibrogenic lung fibroblasts and, when experimentally down-regulated in these cells, promotes senescence and resolution of pulmonary fibrosis." (PMID 31352003, 2019). "Overexpression of HAS2 in lung myofibroblasts leads to a severe fibrotic response and invasive fibroblast phenotype, while the deletion of HAS2 in fibroblasts increases cellular senescence in a mouse model of pulmonary fibrosis." (PMID 30555472, 2018). "In addition, in fibroblasts derived from idiopathic pulmonary fibrosis patients, the overexpression of HAS2 correlated with their ability to invade matrigel." (PMID 29062810, 2017). "Progressive lung fibrosis requires fibroblast differentiation into an invasive myofibroblast phenotype, which is characterized by hyaluronan synthase 2 (HAS2) and CD44 expression and coordinated expression of matrix metalloproteinases (MMPs) and inhibitors of MMP functions." (PMID 29348826, 2017). "Importantly, the study showed that development of lung fibrosis in vivo was also dependent on HAS2 and CD44 expression." (PMID 26583132, 2015). "Furthermore, elevated expression of HAS2 by lung fibroblasts promoted severe lung fibrosis." (PMID 32736577, 2020). "Overexpression of HAS2 by α-SMA positive myofibroblasts produced fatal lung fibrosis, whereas conditional knockout of HAS2 in myofibroblasts reduced the development of lung fibrosis." (PMID 26448760, 2015). "In this study, HAS2-overexpressing transgenic mice showed increased deposition of HA and accumulation and up-regulation of CD44 mRNA and protein in lung myofibroblasts after bleomycin-induced lung injury, resulting in increased lung fibrosis and fatality." (PMID 25954275, 2015).
pancreatic cancer (15 papers, 2013 to 2025). "High expression levels of HAS1 and HAS2 are associated with poor prognosis in various types of cancer, such as ovarian, breast, and pancreatic cancer." (PMID 37636435, 2023). "ROC curves showed that SPHK1 combine with HAS2 has good diagnostic value in pancreatic cancer patients with 85% sensitivity and 99.4% specificity." (PMID 33506044, 2021). "Most importantly, both SPHK1 and HAS2 were significantly associated with short OS of pancreatic cancer patients." (PMID 33506044, 2021). "Kaplan-Meier survival analysis and ROC curve were used to evaluate the prognostic and diagnostic roles of SPHK1 and HAS2 in pancreatic cancer." (PMID 33506044, 2021). "The diagnostic ROC analysis of SPHK1 and HAS2 in TCGA cohort showed that SPHK1 and HAS2 can serve as potential diagnostic biomarkers for pancreatic cancer (P < 0.05)." (PMID 33506044, 2021). "Kaplan-Meier analysis showed that increased expression of SPHK1 and HAS2 was significantly associated with short overall survival (OS) of pancreatic cancer patients." (PMID 33506044, 2021). "Kaplan-Meier analysis showed that increased expression of SPHK1 and HAS2 was associated with short overall survival (OS) of pancreatic cancer patients." (PMID 33506044, 2021). "In PDAC, tumor-associated stromal fibroblasts induce the expression of HAS2 in pancreatic cancer cells, thereby enhancing the rate of synthesis and deposition of hyaluronan." (PMID 29903049, 2018). "Furthermore, in the analysis of gene expression profiles of pancreatic cancer cells and fibroblasts, HAS2 was highly expressed as a differential expression gene and was associated with increased invasiveness of pancreatic cancer cells." (PMID 36698043, 2023). "Our results suggest that Has2/CD44 signaling might be a valid target for patients with TGIF1-deficient pancreatic cancer." (PMID 31109321, 2019). "Furthermore, the combination of SPHK1 and HAS2 could be an effective diagnostic marker for the pancreatic cancer." (PMID 33506044, 2021). "In pancreatic cancer, ETV1 increases the invasive ability of pancreatic cancer cells by regulating two downstream genes Sparc and Has2." (PMID 39668941, 2025). "Then, we investigated the correlation of the SPHK1 and HAS2 expressions with clinical characteristic in pancreatic cancer." (PMID 33506044, 2021). "The prognostic effects of SPHK1 and HAS2 for overall survival (OS) of pancreatic cancer patients were evaluated by Kaplan-Meier survival analysis and the log-rank tests." (PMID 33506044, 2021). "In conclusion, this study demonstrated for the first time that the expression of SPHK1 and HAS2 was markedly increased in pancreatic cancer." (PMID 33506044, 2021). "Then, Spearman correlation analysis was performed, and the results indicated that there is a significantly positive correlation between the expression of SPHK1 and HAS2 in pancreatic cancer." (PMID 33506044, 2021). "The possible potential application of SPHK1 and HAS2 in distinguishing pancreatic cancer was further explored." (PMID 33506044, 2021). "Consistently, the expression of SPHK1 and HAS2 in pancreatic cancer cell lines was significantly increased." (PMID 33506044, 2021). "This study is aimed at investigating the expression of SPHK1 and HAS2 on the prognosis of pancreatic cancer." (PMID 33506044, 2021). "The present study examined the expression of SPHK1 and HAS2 in pancreatic cancer tissues and cell lines, respectively." (PMID 33506044, 2021). "The protein expression of SPHK1 and HAS2 was validated by Western blot, and the results showed that the levels of SPHK1 and HAS2 protein were markedly elevated in pancreatic cancer cell lines compared with normal pancreatic duct epithelial cell line." (PMID 33506044, 2021). "The expression of SPHK1 and HAS2 in pancreatic cancer tissues was analyzed through TCGA and GTEx databases and validated by qRT-PCR and Western blot in pancreatic cancer cell lines." (PMID 33506044, 2021).